SMAD2 (SMAD family member 2)
Diseases named in the same sentence as SMAD2 in open-access papers (continued):
Sharing a sentence is not in itself a finding about the gene and the disease.
oral squamous cell carcinoma (6 papers, 2010 to 2022). "Similarly, the interaction between GDF10 and TGFBR3 regulates epithelial mesenchymal transition and tumor cell resistance through SMAD2/3 pathway in oral squamous cell carcinoma." (PMID 36714584, 2022). "Functional experiments in oral squamous cell carcinoma unraveled that overexpression of GDF10, triggered by type III TGF-β receptor via the TGF-β-SMAD2/3 signaling pathway, resulted in appreciable inhibition in cell proliferation, migration and invasion." (PMID 33407592, 2021). "Moreover, previous research demonstrated that miR-149-5p increased the chemosensitivity of cisplatin on oral squamous cell carcinoma via inhibiting TGF-β2, p-Smad2, and p-Smad3." (PMID 32982740, 2020).
dilatation (5 papers, 2016 to 2025). "Previous studies have shown that pathogenic heterozygous mutations in the SMAD2 gene are implicated in distinct clinical presentations: they are a recognized cause of congenital heart defects (CHTD8) and are also associated with aneurysmal disease." (PMID 41331848, 2025). "This could imply SMAD2-independent mechanisms of ascending aortic dilatation in individuals with AV malformations." (PMID 36104385, 2022). "ZFYVE9 recruits SMAD2 to the TGF-β receptor and was differentially expressed and contributed to aortic dilatation in turner syndrome." (PMID 33083483, 2020). "Therefore, we find it intriguing that ZFYVE9, which recruits SMAD2 to the TGF-β receptor, was differentially expressed and therefore could contribute to aortic dilatation in TS." (PMID 27687697, 2016).
emphysema (5 papers, 2012 to 2024). "Our IHC analysis of p-Smad2 expression in airways and vessels showed upregulation of p-Smad2 in airway and vessel walls of CS-induced emphysema model rats." (PMID 31170951, 2019). "Down-regulation of p-Smad2 expression in emphysema rat lungs may due to imbalanced expression of Smad2 in pulmonary parenchyma and airway-vessels." (PMID 31170951, 2019). "The localization of SMAD2 to alveolar and airway tissue and the decreased TGFβ pathway activity seen with increasing emphysema severity support the hypothesis that a decrease in TGFβ pathway activity also contributes to emphysema pathogenesis." (PMID 22937864, 2012). "UA reduced EMT, EndMT, airway-vessel remodeling, and musculi soleus atrophy in CS-induced emphysema model rats at least partly through IGF1 and TGF-β1/Smad2.3 signaling pathways." (PMID 31170951, 2019).
Glomerular sclerosis (5 papers, 2016 to 2023). Accumulation of scar tissue within the glomerulus. "Another important aspect of renal injury is the SMAD2-dependent down-regulation of miR-30 which is required for TGF-β-induced apoptosis of podocytes in glomerulosclerosis." (PMID 26930277, 2016). "Activation of Smad2/3 promotes the secretion of ECM, leading to glomerular sclerosis and fibrosis, while Smad7 induces apoptosis of podocytes by blocking the activity of NF-kB." (PMID 37538798, 2023).
injury (5 papers, 2016 to 2023). Damage inflicted on the body as the direct or indirect result of an external force, with or without disruption of structural continuity. "Conversely, TGFβ1 signaling via TGFβR/SMAD-2/3 activation is pro-inflammatory in the context of mild traumatic brain injury." (PMID 30940161, 2019). "Moreover, the observed increases in muscle Smad2 activity following CCl4 dosing strongly support a role for TGFβ signaling in the muscle’s response to acute liver injury." (PMID 37509548, 2023).
leiomyoma (5 papers, 2022 to 2026). A well-circumscribed benign smooth muscle neoplasm characterized by the presence of spindle cells with cigar-shaped nuclei, interlacing fascicles, and a whorled pattern. "Research shows Vitamin D3 stops TGF-β3 from activating Smad2 phosphorylation and prevents Smad2 and Smad3 from entering the nucleus in leiomyoma cells." (PMID 41514933, 2026). "In this study, simvastatin significantly suppressed SMAD2 mRNA levels (1.72‐fold) in leiomyoma stem cells." (PMID 35118811, 2022). "In this work, we identified an anti‐leiomyoma stem cell effect of simvastatin by inhibiting the TGF‐β3/SMAD2 and Wnt4/β‐catenin signalling pathways involved in proliferation, differentiation and fibrosis." (PMID 35118811, 2022). "Simvastatin's effect on the TGF‐β3/SMAD2 pathway might explain its inhibitory effect on cell growth and fibrosis in leiomyoma stem cells." (PMID 35118811, 2022). "In line with the ALK4-SMAD2/3-SMAD4 signaling pathway corroborated in this study, the role of activin A in leiomyoma cells is thought to be mediated by activation of the SMAD2/3 signaling pathway." (PMID 38263146, 2024). "We demonstrated that simvastatin reduces SMAD2 and SMAD4 expression in leiomyoma stem cells, whereas it increases the expression of the inhibitory SMAD7." (PMID 35118811, 2022). "In summary, the current evidence confirms the presence of tumour stem cells in leiomyoma and support their role in tumour pathogenesis via TGF‐β3/SMAD2 and Wnt/β‐catenin pathways." (PMID 35118811, 2022). "However, we noted that phospho-Smad2 levels were not reduced following EGCG treatment in leiomyoma cells, suggesting an interesting complexity to EGCG actions." (PMID 37231028, 2023). "However, in both myometrial and leiomyoma cells, activin A and MSTN increase Smad2/3 signaling but do not influence ERK or p38 signaling, suggesting that activin A and MSTN can have antiproliferative and/or fibrotic effects on both cell types via Smad2/3 signaling." (PMID 35780124, 2022).
myeloma (5 papers, 2015 to 2025). "In summary, our results indicated that recombinant GDF15 activated SMAD2 in myeloma cells, possibly through the same receptors as TGF-β." (PMID 29161287, 2017). "Addition of GDF15 dose-dependently and time-dependently activated SMAD2 in THP-1 cells in a manner like in the myeloma cell lines." (PMID 29161287, 2017). "Knockdown of BMPR2 caused potentiation of activin-induced SMAD1/5, but not SMAD2/3, activity in multiple myeloma and hepatocytic carcinoma cells." (PMID 32235336, 2020). "Nevertheless, treatment with either TGF-β or activin A led to phosphorylation of SMAD2, as shown here for the IH-1 and INA-6 myeloma cell lines." (PMID 26047946, 2015). "Activation of the SMAD2/3 pathway did not lead to apoptosis in these cells, likely due to mechanisms that prevent translocation of activated SMAD2/3 to the nucleus in myeloma cells." (PMID 32235336, 2020). "Taken together, we concluded that activin A inhibited BMP-9 signaling in myeloma cells through a mechanism that was independent of activation of SMAD2 through ALK4 or ALK7." (PMID 26047946, 2015). "We found that recombinant human GDF15 activated SMAD2, but not SMAD1/5 in the multiple myeloma cell line IH-1." (PMID 29161287, 2017).
oral submucous fibrosis (5 papers, 2020 to 2025). "YBX1 promotes the expression of α-SMA and p-Smad2 along with the progression of human buccal mucosal fibroblasts to myofibroblasts transition in oral submucous fibrosis, which correlates with TGF-β signaling pathway." (PMID 40346063, 2025).
ovarian tumor (5 papers, 2010 to 2021). "To understand the roles of SMAD2 in ovarian tumor development in inhibin-deficient mice, we took advantage of a conditional knockout strategy to disrupt the Smad2 gene in mouse ovarian granulosa cells." (PMID 20565978, 2010). "Within the mouse tumor cell lines, the ovarian tumor-derived OVdT4088 and OVdT4306 cancer cells expressed the TGFβ downstream target phosphorylated Smad2, while the Dicer-Pten DKO cancer cell lines showed very little expression." (PMID 27602775, 2016). "The aim of the current study was to define the role of SMAD2 in the development of ovarian tumors and activin-induced cancer cachexia syndrome." (PMID 20565978, 2010). "Next, to uncover potential effect of Smad2 deletion on ovarian tumor development at an early stage, we examined the tumor status in the Smad2flox/-; Inha-/-; Amhr2cre/+ mice at various time points between 4 and 9 weeks of age, since inhibin-deficient mice can develop tumors as early as 4 weeks." (PMID 20565978, 2010). "SMAD2 is not required for mediating tumorigenic signals of activin in ovarian tumor development caused by loss of inhibin." (PMID 20565978, 2010). "In the case of conditional deletion of Smad2, SMAD3 compensates for the deficiency of SMAD2 and transduces essential signals contributing to ovarian tumor development; consequently, tumorigenesis is not altered." (PMID 20565978, 2010). "Our results indicate that SMAD2 ablation does not protect inhibin-deficient females from the development of ovarian tumors or the cachexia wasting syndrome." (PMID 20565978, 2010). "Because activins signal through SMAD2 and SMAD3 in vitro and loss of SMAD3 attenuates ovarian tumor development in inhibin-deficient females, we sought to determine the role of SMAD2 in the development of ovarian tumors originating from the granulosa cell lineage." (PMID 20565978, 2010). "On the other hand, loss of SMAD3 in the Inha null mice attenuates but does not prevent ovarian tumor development, suggesting that SMAD2 may partially compensate for the loss of SMAD3." (PMID 20565978, 2010). "Somewhat unexpected, our further analysis showed that ovarian tumor tissues which barely contained oocytes readily expressed TGFBR1CA, along with increased levels of phospho-SMAD2/3 and reduced expression of HSD3B in comparison to controls." (PMID 29221447, 2017). "However, our model does not rule out the potential involvement of SMAD-independent signaling in inhibin-deficient ovarian tumor development or the possibility that SMAD2 may not be involved in gonadal tumor development." (PMID 20565978, 2010). "We also examined p-SMAD2 and EMT markers in primary ovarian tumors using Western blot." (PMID 35004276, 2021). "Since deletion of SMAD3 only delays ovarian tumor development in the Inha null mice, we were interested in determining the potential involvement of SMAD2 in mediating the potentiated activin signaling in ovarian tumors lacking inhibins." (PMID 20565978, 2010). "In the absence of inhibins, ovarian tumors were grossly hemorrhagic and contained blood-filled cysts irrespective of the status of SMAD2." (PMID 20565978, 2010). "Thus, conditional deletion of Smad2 does not delay ovarian tumor development and the progression of the cachexia wasting syndrome in inhibin-deficient mice." (PMID 20565978, 2010).
thyroid cancer (5 papers, 2019 to 2025). "Conditional media from CAFs overexpressing PROS1 significantly upregulated the expression of β‐catenin, C‐myc, CCND1, and p‐SMAD2 in thyroid cancer cells." (PMID 40433916, 2025). "As shown, most cancers were exhibited as SMAD2 positive, such as colorectal, endometrial, ovarian, renal and thyroid cancers, which indicated that SMAD2 widely expressed in a variety of cancer cells." (PMID 33202380, 2020). "Moreover, EIF5A2 could modulate TGF-/Smad2/3 signal in thyroid carcinoma." (PMID 35064108, 2022).
type 1 diabetes (5 papers, 2018 to 2024). "TGF-β can mediate RNA processing through the Smad2/3 pathway, activate the secretion of miR-140-3P and miR-143-3P, reduce the number and activity of islet cells, and ultimately mediate the apoptosis of islet cells, which can lead to type 1 diabetes." (PMID 39705488, 2024). "L-Fucose could promote neurogenesis and gliogenesis derived from ENPCs by inhibiting the SMAD2 signaling, thus facilitating ENS regeneration and gastrointestinal motility recovery in type 1 diabetic mice." (PMID 37798789, 2023).
type 2 diabetes (5 papers, 2017 to 2026). "Moreover, the Chinese herbal medicine Tangshen Formula appears to attenuate colonic structure remodeling in type 2 diabetic rats possibly by inhibiting the overactivated pathway of NF-κB and therefore reducing expression of TGF-β1/Smad2/3." (PMID 28303157, 2017).
Cognitive impairment (4 papers, 2022 to 2025). Abnormal cognition is characterized by deficits in thinking, reasoning, or remembering. "Increased TGF-β1 promotes the phosphorylation and nuclear translocation of Smad2/3, sequentially activating the transcription of Sp1, which is regarded as a key feature of AngII-induced synaptic and cognitive impairments." (PMID 40425782, 2025). "In an APP/APOE knockout mouse, inhibition of the TGFB/SMAD2 pathway activity in astrocytes has been shown to increase amyloid plaque formation and cognitive impairment." (PMID 35573689, 2022). "Additionally, downregulating TGF-β1 ameliorated synaptic and cognitive impairments by inhibiting the Smad2/3 axis." (PMID 40425782, 2025). "Increased TGF-β1 leads to elevated Smad2/3 phosphorylation resulting in the Smad2/3 then translocation into the nucleus, enhancing the activity of the transcription factor Sp1, which mediates synaptic and cognitive deficits." (PMID 40425782, 2025). "This occurs as the result of increased TGF-β1 that upregulates the phosphorylation of Smad2/3, which then leads to the nuclear translocation of Smad complex may trigger the transcription of Sp1 and ultimately leading to synaptic damage and cognitive impairments." (PMID 40425782, 2025). "Induction of AD using ICV-STZ injection resulted in significant cognitive impairment, oxidative stress, defective Aβ clearance, and histopathological abnormalities that may be attributable to the upsurged TGF-β1/p-Smad2/p21 signaling." (PMID 39708240, 2024). "However, in the development of cognitive impairment postoperation, the elevated Smad7 interacts with TGF-β receptor type I, thus inhibiting the phosphorylation of Smad2/3." (PMID 37507781, 2023). "To evaluate whether Smad7 is involved in the occurrence of cognitive impairment after anesthesia and surgery by regulating the TGF-β1-related signaling pathway, we detected the protein expression of Smad2/3, Smad4 and phosphorylated Smad2/3 in the hippocampus in wild-type mice and Smad7−/− mice." (PMID 37507781, 2023).
colorectal adenocarcinoma (4 papers, 2014 to 2025). The most common type of colorectal carcinoma. "Chromosome 18q is the location of the DCC, DPC4 (SMAD4; MADH4), and JV-18 (SMAD2; MADH2) genes, and loss is frequent in colorectal adenocarcinoma." (PMID 37509254, 2023). "Three of the twenty-one genes predicted to be affected by these miRNAs—SMAD2, SMAD4, and TGFBR2—were shared between pathways related to colorectal adenocarcinoma (COAD) and TGF-β signaling." (PMID 40868288, 2025).
colorectal tumours (4 papers, 2014 to 2023). "Despite the majority of CRCs having deactivating TGF‐β pathway mutations (TGFBR1, TGFBR2, SMAD4, SMAD2, SMAD3), colorectal tumours produce significant amounts of TGF‐β, creating a TGF‐β rich environment, to which only the stromal compartment can respond." (PMID 35595718, 2022). "From somatic studies, SMAD4 is not seen to be a driver gene for GI cancer, though 16% of primary colorectal tumours have alterations in SMAD4, and 6% in SMAD2." (PMID 38066625, 2023).
depression (4 papers, 2019 to 2026). "The present study shows that SA4503 ameliorates excitation propagation disorder, increases atrial conduction velocity, and improves inflammatory factors by TGF-/Smad2/3 signaling in a rat depression model." (PMID 31803058, 2019). "Additionally, the down-regulation of phosphorylated SMAD2/3, phosphorylated NF-κB, phosphorylated ERK1/2, and phosphorylated JNK also proved to be crucial indicators of the improvement of depression symptoms." (PMID 33613190, 2020).
dyslipidemia (4 papers, 2017 to 2025). "In conclusion, PP ameliorated kidney dysfunction and fibrosis through attenuating dyslipidemia, anti‐oxidative stress, and inhibiting the activation of TGFβ/Smad2 signaling pathway in db/db mice." (PMID 40688601, 2025). "Lox-1/PKC-α/MMP9 was upregulated by dyslipidemia, and those signal pathways increased TGF-β and SMAD2/3, which induced EndMT." (PMID 33574986, 2021). "In dyslipidemia, the increased levels of oxidized low-density lipoproteins (oxLDL) upregulated the lectin-type oxidized LDL receptor 1 (Lox-1), which then upregulated the down signaling pathways of PKC-α/MMPs/TGF-β/SMAD2 or 3 and increased the EndMT." (PMID 33574986, 2021).
endothelial dysfunction (4 papers, 2021 to 2024). In vascular diseases, endothelial dysfunction is a systemic pathological state of the endothelium (the inner lining of blood vessels) and can be broadly defined as an imbalance between vasodilating and vasoconstricting substances produced by (or acting on) the endothelium. "However, other reports have demonstrated that Smad2/3 silencing blocked TGF-β2’s effect on endothelial dysfunction." (PMID 38383474, 2024). "The underlying mechanism lies in SMAD2/3 phosphorylation, which increases the production of NADPH oxidase 2 (NOX2), a primary source of reactive oxygen species in the endothelial cells resulting in endothelial dysfunction." (PMID 37595293, 2023). "However, there were also situations in which the transfection of EVs with Smad2/3 siRNA had a better effect, amplifying the ability of ADSCs or MSCs to regress endothelial dysfunction or even the administration as such of Smad2/3 siRNA had a better effect." (PMID 35478972, 2022). "Also, the influences of siRNA-targeting Smad2/3 (Smad2/3siRNA) on endothelial dysfunction and its key molecular players were analyzed." (PMID 35478972, 2022).
experimental autoimmune encephalomyelitis (4 papers, 2017 to 2026). An autoimmune demyelinating disease of the central nervous system that is produced experimentally in animals by the injection of homogenized brain or spinal cord in Freund's adjuvant. "This notion is consistent with the previous findings that T-cell-specific deficiency of Smad2 leads to impaired Th17 differentiation and alleviated clinical symptoms in mouse disease models including experimental autoimmune encephalomyelitis and CIA." (PMID 28615031, 2017). "This dual action-sustained STAT5 activation and increased Smad2/3 signaling-promoted robust Treg generation that ameliorated experimental autoimmune encephalomyelitis (EAE)." (PMID 42086904, 2026).
gastric tumors (4 papers, 2010 to 2025). "In fact, Overexpression of Smad2 was associated with metastasis, and was correlated with poor prognosis of gastric tumors especially diffuse-type gastric carcinoma." (PMID 21110833, 2010). "In the HER2-positive gastric tumors, the expression status of both p-Smad2 and c-Met was positive in both the primary tumor and metastatic lymph nodes, and the p-Smad2 and c-Met expression levels in the metastatic lymph nodes tended to be higher than those in the primary tumors." (PMID 35650563, 2022). "We previously demonstrated the clinicopathological significance of several cancer-associated molecules including fibroblast growth factor receptor 2 (FGFR2), transforming growth factor-beta 1 (TGFβ1), C-X-C chemokine receptor 2 (CXCR2), CXCR4, and phospho-Smad2 expressed at primary gastric tumors." (PMID 35650563, 2022).
glaucoma (4 papers, 2020 to 2022). Increased pressure in the eyeball due to obstruction of the outflow of aqueous humor. "If miR-486-5p could target SMAD2 in TMCs, elevated ECM remodeling may be detected in glaucoma patients." (PMID 35251709, 2022). "Since elevated levels of TGF‐β, EndMT (endothelial‐to‐mesenchymal transition) and fibrogenic activities are presumed to play a part in ocular hypertension and glaucoma, we determined the effects of vasorin on TGF‐β2 mediated activation of SMAD2/3, and expression of α‐SMA and fibronectin in TM cells." (PMID 35170203, 2022). "If this miRNA also targets SMAD2 in TM cells, this may contribute to the increased ECM remodeling observed in glaucoma patients e.g. increase production of fibronectin that leads to increased stiffness and reduced AH outflow." (PMID 34156425, 2021).